TRIM59 (tripartite motif containing 59)
Diseases named in the same sentence as TRIM59 in open-access papers (continued):
Sharing a sentence is not in itself a finding about the gene and the disease.
tumor (continued). "To determine whether macrophages educated by TRIM59 contribute to the promotion of tumor characteristics, we conducted a set of experiments in vitro." (PMID 32867817, 2020). "Overexpression of TRIM59 mRNA in tumor tissues predicted poor prognosis." (PMID 31948534, 2020). "However, the mechanisms of TRIM59 promoting cancer metastasis and the communication between the tumor microenvironment and tumor cells are still waiting for exposure." (PMID 32867817, 2020). "First, TRIM59 can be transferred by exosomes from tumor cells to macrophages." (PMID 32867817, 2020). "Increasing evidence showed that TRIM59 has been identified as contributing to tumor progression." (PMID 32867817, 2020). "In addition to reports that TRIM59 can be knocked out to inhibit the proliferation of CCA, other DERNAs were reported for the first time to show differences between tumour and normal tissue and were significantly associated with the prognosis of CCA patients." (PMID 32336950, 2020). "The expression level of TRIM59 protein was significantly higher in tumor tissues than in adjacent tissues, and TRIM59 protein expression was correlated with tumor size (P=0.007), tumor differentiation (P=0.009), tumor-node-metastasis (TNM) stage (P=0.003) and lymph node metastasis (P=0.003)." (PMID 31948534, 2020). "Cox regression analysis showed that TRIM59 was an independent prognostic factor in tumor tissues." (PMID 31770215, 2019). "Our results support and expand previous research suggesting that TRIM59 expression in macrophages critically modulates metastasis in tumor cells, and may be a valuable target for cancer immunotherapy." (PMID 31600735, 2019). "To determine whether TRIM59 governs tumour growth and invasion in vivo, we further examined the effects of TRIM59 expression on in vivo tumour growth of LC cells." (PMID 30515965, 2019). "Mean tumor volume was significantly greater in TRIM59-CKO mice compared to WT mice." (PMID 31600735, 2019). "KO of either TRIM59 or PDCD10 suppressed MCF7 xenograft tumor growth to a similar extent." (PMID 30408026, 2018). "Notably, TRIM59-deficient MCF7-luc cells acquired a growth advantage later (around 12 weeks postinjection, KO tumor size was comparable to control or KO+OE group), but the metastatic ability was greatly reduced (middle)." (PMID 30408026, 2018). "Importantly, we uncovered TRIM59 as a key regulator of cell contractility and adhesion to control the plasticity of metastatic tumor cells." (PMID 30408026, 2018). "Furthermore, TRIM59 silencing diminished tumor size in a tumorigenic model in nude mice." (PMID 33498521, 2021). "Thus, the data implicate TRIM59 as a target for exosome-mediated tumor immune evasion." (PMID 32867817, 2020). "When viewed in combination, it is tempting to speculate that the heterogeneity and dynamic nature of tumor microenvironment across different cancers, as well as different stages of the same cancer, it is quite likely that the function of TRIM59 in TAMs might also vary across these conditions." (PMID 32867817, 2020). "Moreover, they highlight the relevance of TRIM59 in macrophages as a potential regulator of tumor metastasis and suggest TRIM59 could serve as a novel target for cancer immunotherapy." (PMID 31600735, 2019). "However, the prognostic value of TRIM59 in the survival of tumor patients remains controversial." (PMID 31770215, 2019). "Thus, TRIM59 appears to be the critical oncoprotein in regulating tumour cell invasion." (PMID 30515965, 2019). "However, the mechanism(s) by which TRIM59 expression in macrophages, and especially in TAMs, influences tumor cell activity and survival remains unclear." (PMID 31600735, 2019).
tumor (continued). "Functional studies revealed that knockdown of TRIM59 inhibited CRPC cell proliferation, migration, and tumor growth." (PMID 40723250, 2025). "Tripartite motif-containing 59 (TRIM59), a surface molecule belonging to the TRIM family, plays a role in tumor proliferation and migration." (PMID 40558830, 2025). "By modulating ferroptosis, lipid raft dynamics, and energy metabolism, E3 ligases such as RNF126, TRIM59, and FBW7 enable tumors to adapt to metabolic stress and evade apoptosis, making them promising targets for disrupting tumor lipid reprogramming." (PMID 40370434, 2025). "To explore the diagnosis efficacy of TRIM59, we performed ROC and SROC analyses to identify that high expression of TRIM59 showed a high diagnosis efficacy in each tumor type (AUC > 0.5), and with an AUC of summary ROC of 0.94 (0.91–0.96)." (PMID 34534244, 2021). "Therefore, TRIM59 may be considered a novel multiple tumor marker for early detection." (PMID 30389710, 2019). "Taken together, these results suggest that TNF-α production by TRIM59-/--M2 macrophages promotes the expression of MMP-9 and Madcam1 in B16-F0 and B16-F10 tumor cells, enhancing their metastatic potential." (PMID 31600735, 2019). "TRIM59, a member of the TRIM family, has been reported to play a role in several types of human tumor." (PMID 30389710, 2019). "To assess the effects of MMP-9 and Madcam1 deletion on tumor growth in vivo, we subcutaneously injected B16-F10 cells transfected with shRNA-MMP-9, shRNA-Madcam1, or scrambled control-shRNA into WT or TRIM59-CKO mice." (PMID 31600735, 2019). "TRIM59, a member of the TRIM family, has been reported to participate in several type of human tumor." (PMID 30389710, 2019). "By comparison, mammary xenograft tumor growth was greatly accelerated in mice bearing TRIM59 OE MDA-MB-231 cells, with a notable increase in tumor sizes." (PMID 30408026, 2018). "Mechanistically, TRIM59 interacts with interferon regulatory factor 3 (IRF3) and promotes its ubiquitination and proteasomal degradation, thereby inhibiting the IRF3-STING pathway and downstream anti-tumor interferon production." (PMID 42245669, 2026). "Our research demonstrated that TRIM59 facilitates ACAT1 ubiquitination in pRCC, thereby reducing endocytic phospholipid synthesis and inhibiting mitochondria-dependent apoptosis, ultimately promoting tumor growth." (PMID 40790033, 2025). "Then, we used the vitro culture model to mimic the local tumor microenvironment, by using concentrated conditioned medium (CCM) from THP-1 macrophages infected with lentiviral vectors expressing TRIM59 or GFP control in the presence of the LPS and ATP stimulation." (PMID 32867817, 2020). "Compared with the shRNA control, TRIM59 knockdown decreased expression of p-STAT3, proliferation marker Ki-67, and cancer cell stemness marker CD44, whereas the levels of mH2A1 was elevated in GSC xenograft tumor tissues by immunohistochemical (IHC) analyses." (PMID 31488827, 2019). "The relationship between TRIM59 and carcinogenesis has been described in several in vitro studies, and some studies have clarified the relationship between TRIM59 and the prognosis of one tumor, but not systematically." (PMID 31770215, 2019). "In human samples, Spearman correlation analysis based on Clinical Proteomic Tumor Analysis Consortium (CPTAC) also revealed a negative correlation between TRIM59 expression and phosphorylation of ezrin (R = −0.23)." (PMID 30408026, 2018). "Loss of PDCD10 decreased the stability of VEGFR2 protein, hinting that TRIM59 might stabilize VEGFR2 protein through PDCD10 to augment VEGF signaling and tumor angiogenesis." (PMID 30408026, 2018). "However, the pro-oncogenic role of TRIM59 in the tumor microenvironment have not yet been identified." (PMID 32867817, 2020).
tumor (continued). "To test whether TRIM59 promote cancer cell growth and invasion through regulation of the ERK signalling pathway, we further examined the effects of ERK pathway activation on tumour proliferation and invasion of H1299 and A549 cells." (PMID 30515965, 2019). "However, the use of TRIM59 as tumor diagnosis and prognosis biomarker has not been fully explored." (PMID 34534244, 2021). "However, results from these studies were limited by a small number of tumor samples, or the use of in vitro experimentation or animal models could not fully address the relationship between TRIM59 and human cancers." (PMID 34534244, 2021).
cancer (32 papers, 2017 to 2026). A tumor composed of atypical neoplastic, often pleomorphic cells that invade other tissues. "Our analysis revealed that high expression of TRIM59 is associated with poor prognoses in cancer patients." (PMID 31770215, 2019). "Immunohistochemical analysis shows that TRIM59 expression is significantly up-regulated in multiple human cancers and overexpressed TRIM59 is associated with tumorigenesis and progression." (PMID 31820796, 2019). "Additionally, many studies have investigated the specific association of TRIM59 with tumorigenesis in each respective cancer field." (PMID 31770215, 2019). "Our unbiased comparative analysis revealed the differential expression/phosphorylation of at least nine key cancer-associated signaling proteins, which might be directly or indirectly affected upon alteration of TRIM59." (PMID 30408026, 2018). "To confirm that TRIM59 is an independent factor linked to clinical outcomes, we performed multivariate overall survival analysis by using a Cox proportional hazard model based on available clinical information, including patient cancer stages and pathological grades." (PMID 30408026, 2018). "We aimed to investigate the expression of TRIM59 in pan-cancer as well as its implications for tumorigenesis, clinicopathological factors, and immune cell infiltration." (PMID 41710851, 2026). "Collectively, these findings, along with our results, suggest that TRIM59 performs numerous complex functions, including glycolysis, which is crucial for cancer progression." (PMID 40796729, 2025). "Specifically, TRIM14, TRIM25, TRIM32, TRIM44, TRIM59, and TRIM29 exhibit abnormal expression in different cancer types and have been linked to patient prognosis." (PMID 39273003, 2024). "Recent evidence on tripartite motif containing 59 (TRIM59) indicates that it is involved in the chemoresistance of various cancers." (PMID 39725730, 2024). "Several studies have investigated the modulatory effects of TRIMs on oncogenic proteins or drug-induced cancer: the TRIM59 gene was upregulated in SV40 (simian vacuolating virus 40) Tag oncogene-directed transgenic and knockout mouse prostate cancer models." (PMID 36261847, 2022). "Several TRIM genes exhibited similar expression patterns in various cancer types, such as TRIM28 and TRIM59, which were extensively highly expressed in cancer." (PMID 36461099, 2022). "TRIM44 and TRIM59, identified as oncogenes, are enriched in cancers and involved ininvasion stimulus, which predicts poor prognosis." (PMID 34284744, 2021). "Our results extend our knowledge regarding the regulation of TRIM59 and potential targets for the development of novel therapeutic approaches targeting cancer metastasis." (PMID 32867817, 2020). "With the unraveling of the relationship between TRIM59 and tumors, TRIM59 is now being recognized as potential therapeutic targets for cancer." (PMID 32867817, 2020). "A number of gene nodes linked to drug resistance in other cancer types (including CAT, TRIM59, ANXA2, ADM, AJUBA, HSPA1A/1B, LAMC2, TRIM14, KRT8, KRT18, KRT9, CLDN1, and SMARCA2) were also down-regulated in PARPis-sensitive AsPCs." (PMID 33213473, 2020). "We therefore conducted this meta-analysis to obtain a more definitive conclusion on the relationship between TRIM59 and cancer-related survival." (PMID 31770215, 2019). "The aim of our meta-analysis was therefore to provide a quantitative assessment of the prognostic value of TRIM59 in various types of cancer." (PMID 31770215, 2019). "In recent years, many research studies have shown that TRIM family proteins, such as TRIM3, TRIM11, TRIM19, TRIM31, TRIM44 and TRIM59 have been demonstrated to serve a significant role in the tumorigenesis and progression of numerous cancer types." (PMID 30484263, 2019).
cancer (continued). "As expected, the expression of CDK6 was significantly inhibited by ERK inhibitor in TRIM59 overexpressed cancer cells." (PMID 30515965, 2019). "We therefore conducted a meta-analysis to assess the prognostic significance of TRIM59 in cancer patients." (PMID 31770215, 2019). "The results showed that high levels of TRIM59 were significantly associated with poor OS in cancer patients (HR = 1.43, 95%CI: 1.24–1.66, P < .001), indicating that higher TRIM59 expression could be an independent prognostic factor for poor survival in cancer patients." (PMID 31770215, 2019). "In basic laboratory research, TRIM59 has been shown to promote the migration and invasion of cancer cells, and knockdown of TRIM59 inhibits malignancy processes in human cancer cells." (PMID 31770215, 2019). "This meta-analysis revealed that high TRIM59 expression is a predictor of poor OS in cancer patients." (PMID 31770215, 2019). "Among the approximately 70 members in the TRIM family, TRIM59 stood out as one of the most differentially expressed genes, with its expression ubiquitously up-regulated by 1.6- to 6.3-fold in 12 analyzed cancer types compared with the adjacent normal tissues." (PMID 30408026, 2018). "Among these, TRIM59 has emerged as a potential oncogene in multiple cancers; however, its role in pRCC progression remains unclear." (PMID 40790033, 2025). "Consequently, further research is needed to elucidate the specific mechanisms by which TRIM59 regulates macrophages in different types of cancer." (PMID 38992114, 2024). "TRIM59 emerges as a promising multi-cancer biomarker with potential synergistic implications." (PMID 37867509, 2023). "TRIM11, TRIM27, TRIM28 and TRIM59 have higher expression in almost all cancers." (PMID 36461099, 2022). "Additionally, TRIM family proteins participate in the regulation of cytokine gene transcription, and TRIM59 is upregulated in various cancers and promotes the development of tumors." (PMID 35693774, 2022). "Thanks to the gene expression data and associated prognosis information provided in public database, we identified that TRIM59 was highly expressed in most solid tumors and could indicate the prognosis in several cancers." (PMID 34534244, 2021). "TRIM59 is upregulated in various cancers and promotes the development of tumors." (PMID 32133014, 2020). "TRIM59 may therefore serve as a promising prognostic biomarker that can be utilized to improve future cancer therapies." (PMID 31770215, 2019). "Our meta-analysis suggests that higher TRIM59 expression predicts poor prognosis in cancer patients, and it may therefore serve as a promising prognostic factor." (PMID 31770215, 2019). "With the advances in the study of TRIM59, researchers have found that TRIM59 is involved in a variety of malignant biological behaviors in tumors, which suggests that TRIM59 has the potential to be a target for future cancer therapies." (PMID 31770215, 2019). "In 2011, TRIM59 was initially found to act as a potential oncoprotein in a mouse model of cancer." (PMID 31770215, 2019). "In this study, we have uncovered a previously uncharacterized role of TRIM59 in modulating the motility modes and metastasis of cancer cells through coordinated actions of the adhesion molecules and the organization of actin/myosin (actomyosin)-mediated cell contractility." (PMID 30408026, 2018). "Similarly, overexpression of TRIM59 in MDA-MB-231-luc cells promoted cancer cell metastasis at approximately 6 weeks postinjection and greatly shortened survival, because the mice died at 10 weeks." (PMID 30408026, 2018). "The TRIM59 gene is a novel multiple carcinoma marker which may be used for molecular-targeted diagnosis and therapy of cancer." (PMID 28009992, 2017). "Current research focused on the function of TRIM59 in various types of cancer and has demonstrated that TRIM59 can regulate the PI3K/AKT signal pathway in various cancers." (PMID 32133014, 2020).
cancer (continued). "TRIM59 is found, among all the TRIM genes, to be the only member displaying marked up-regulation across all 12 cancer types in The Cancer Genome Atlas (TCGA) database, suggesting a probably oncogenic function of it in human cancers." (PMID 31820796, 2019). "Thus, this review will focus mainly on the crosstalk of the signaling pathways in cancer development, especially the ones that involve widely studied TRIM proteins, i.e., TRIM28, TRIM25 and TRIM59." (PMID 39451518, 2024). "Furthermore, we further investigated the mechanisms that TRIM59 positively regulates CDK6 expression by activation of ERK pathway, which contribute to cancer cell growth and invasion." (PMID 30515965, 2019). "Our study of the mechanisms by which TRIM59 controls cell plasticity through regulating PDCD10 stability and the downstream RhoA-ROCK signaling may provide novel insights into the regulatory network of cancer cell invasion and metastasis." (PMID 30408026, 2018).
infection (3 papers, 2017 to 2024). The state of being infected such as from the introduction of a foreign agent such as serum, vaccine, antigenic substance or organism. "TRIM59 also maintained a repressed state throughout early infection, followed by a strong activation at 16 h of infection." (PMID 28993767, 2017). "TRIMs specific to the infection (TRIM59 for P. aeruginosa, TRIM67 for Chlamydia spp)." (PMID 37686095, 2023). "infections (TRIM5, 13, 14, 15, 18, 19, 20, 21, 22, 25, 26, 31, 35, 36, 37, 50, 55, 56, 61, 63, 65, 69, and 71) were up-regulated following TLR stimulation and/or by IFNs, while TRIM59 and TRIM66 were down-regulated under these conditions and upon P. aeruginosa infection." (PMID 37686095, 2023).
colorectal (1 paper, 2024). "We found that the deficiency of TRIM59 in macrophages inhibited colorectal tumorigenesis in mice." (PMID 38992114, 2024).
TRIM59 also shares sentences with these, for which no sentence is quoted: ovarian carcinoma (3 papers); acute respiratory distress syndrome (2); colon carcinoma (2); Lung Squamous Cell Carcinoma (2); osteosarcoma (2); alcoholic fatty liver disease (1); immune diseases (1); kidney cancer (1); laryngeal squamous cell carcinoma (1); metastasis (1); osteoarthritis (1); pancreatic cancer (1); papillary renal cell carcinoma (1); pulmonary hypertension (1); squamous cell carcinoma (1); stomach adenocarcinoma (1).